CCL3 (C-C motif chemokine ligand 3)
Diseases named in the same sentence as CCL3 in open-access papers (continued):
Sharing a sentence is not in itself a finding about the gene and the disease.
colitis (continued). "In this study, we demonstrated that the loss of VDUP1 enhanced macrophage infiltration in DSS-induced colitis, which was accompanied by a significant increase in the mRNA expression of macrophage-attracting chemokines, including CCL2, CCL3, and KC in inflamed colon tissues." (PMID 37686390, 2023). "Moreover, L. acidophilus NCFM and FAHWH11L56 showed similar effects on various indicators of DSS-induced colitis, increasing the IL-10 and IL-17 in the colon, and modifying the CCL2/CCR2 axis and CCL3/CCR1 axis." (PMID 36499169, 2022). "For L. acidophilus FGSYC48L79, although it blocked the CCL2/CCR2 axis, it can promote the signal transmission on the CCL3/CCR1 axis, which may be one of the reasons why this strain appeared to have the effect of worsening colitis." (PMID 36499169, 2022). "Furthermore, VDUP1-KO mice exhibited increased mRNA expression of macrophage-attractive chemokines, including C-C motif chemokine ligand 2 (CCL2/MCP-1), C-C motif chemokine ligand 3 (CCL3/MIP1A), and keratinocyte chemoattractant (KC/CXCL1) in mice with DSS-induced colitis compared to WT mice." (PMID 37686390, 2023). "A 16-gene signature (CARD12, CCL3, CCR3, CXCL1, F5, FAM210B, GADD45A, IL18bp, IL2RA, IL5, IL8, MMP9, PTGS2, SOCS3, TLR9 and UBE2C) was identified from 30 days post-tremelimumab initiation blood that discriminated patients developing grade 0–1 from grade 2–4 diarrhea/colitis." (PMID 30227886, 2018). "Interestingly, it was suggested that CCR5 inhibition reduces infiltration of both innate and adaptive immune cells, which leads to reduced inflammation in the colon during colitis and CRC, although CCR5 might interact with other ligands, based on the comparable levels of expression of CCL3." (PMID 30429227, 2018).
influenza (49 papers, 2009 to 2026). An acute viral infection of the respiratory tract, occurring in isolated cases, in epidemics, or in pandemics; it is caused by serologically different strains of viruses (influenzaviruses) designated A, B, and C, has a 3-day incubation period, and usually lasts for 3 to 10 days. "In contrast, levels of IL-1RA, IL-2, TNF-α, CCL3, and G-CSF were more increased among pandemic influenza A(H1N1) patients." (PMID 33995342, 2021). "Levels of IL-6, IL-8, TNF-α, and CCL3 were also increased in our cohort of pandemic influenza A(H1N1) patients, validating our previous observations." (PMID 33995342, 2021). "Influenza infection also induces the production of such cytokines as TNFa, IL-1, IL-6, and the mononuclear cell attractant chemokines: CCL-3, CCL-4, CCL-5, CXCL9, CXCL10, and CXCL11 in human monocytes, epithelial cells, and rat alveolar or murine macrophages." (PMID 30037133, 2018). "The up-regulation of IL-8, IFNγ and CCL3 has been related to lung recruitment of neutrophils, NK and T cells and the development of severe influenza infection." (PMID 27825367, 2016). "It has previously been demonstrated that co-administration of antigens and CCL3 or fusion of antigen to CCL3 increased the antigen-specific CD8+ T cell responses to for example influenza and HIV-1." (PMID 26494531, 2015). "In combination with hemagglutinin from influenza or ovalbumin, targeting by use of αMHCII generated higher antibody levels than targeting by CCL3." (PMID 25122197, 2014). "Cytokines such as IL-4, IL-5, IL-6, IL-8, IL-13, and TNF-α, chemokines such as CCL2 and CCL3, and the MC proteases tryptase and chymase can be detected in the supernatants of influenza infected MC cultures and in the bronchioalveolar lavage fluid (BALF) of both influenza patients and infected mice." (PMID 33680987, 2021). "The available data suggests that, while CCL5 can play a protective role in influenza infection, CCL3 may contribute to an overwhelming inflammatory process that can harm the lung tissue." (PMID 35126379, 2021). "Consequently, Xcl1-HA induced superior protection against influenza infection compared to Ccl3-HA after i.d. immunization." (PMID 30755656, 2019). "The suite of cytokines and chemokines assessed here, namely, TNF-α, IL-6, CCL2, CCL3, CXCL2 and IL-1β, are known to promote the inflammation caused by influenza at early stages of the infection phase, i.e. during the cytokine storm, and have been shown to underpin the pathology and morbidity." (PMID 23577160, 2013). "Currently, the information obtained by the use of animal models suggests that while some CCR5 ligands, like CCL5, can play a protective role in influenza infection others, like CCL3, may contribute to an overwhelming inflammatory process which can harm the lung tissue." (PMID 35126379, 2021). "The production of several chemokines involved in influenza severity, including CCL2/MCP-1, CCL3/MIP-1α, CCL4/MIP-1β, CCL5/RANTES, CXCL2/MIP-2, and CXCL10/IP-10 was also quantified." (PMID 40612502, 2025). "We observed increased expression of Stat1, Stat2, Mx1, Oasl2, CCL2, CCL3, CXCL9, and CXCL10 in influenza-infected hearts and lungs when compared to PBS-treated controls." (PMID 38750107, 2024). "In our study, we found increased expression of CCL2, CCL3, CXCL9, and CXCL10 in the heart following PR8, pH1N1, or H3N2 strains of influenza infection." (PMID 38750107, 2024). "The study also revealed strengthened interactions of the Ccl5-Ccr5, Ccl4-Ccr5, and Ccl3-Ccr5 ligand/receptor pairs between CD8+ Trm and other memory subsets after influenza infection." (PMID 37415817, 2023). "Role of Hypercytokinemia/hyperchemokinemia in the Pathogenesis of Influenza pathway was found to be significantly upregulated in the severe group’s monocytes with DEGs of AREG, CCL3, CCL4, CXCL8, IL1B, and ISG15 (coverage = 7% and p < 0.001)." (PMID 37495649, 2023).
influenza (continued). "During influenza, cytokines and chemokines such as type I and III interferons (IFNs), IL-6, CXCL8, CCL2, CCL3, CCL4, and CCL5 are produced at the site of infection (Wareing and others 2004)." (PMID 35674675, 2022). "CCL3 and CXCL10 are known to trigger the infiltration of macrophages in influenza infection yet, despite the decrease in these chemokines, there was no change in the number of macrophages in the infected NOX4 TG." (PMID 35601109, 2022). "Influenza infected NOX4 TG mice had decreased expression of CXCL10, CCL3, CXCL1 and CXCL2 three days post infection." (PMID 35601109, 2022). "Chemokine receptor 5 (CCR5) and its cognate chemokines CCL3, CCL4 and CCL5 are rapidly induced upon influenza infection, contributing to leukocyte recruitment into the airways and a consequent effective antiviral response." (PMID 35126379, 2021). "CCL3 and CCL4, the other CCR5 ligands, are also expressed in response to experimental influenza infection in human volunteers." (PMID 35126379, 2021). "Other chemokines elevated in influenza-infected Tpl2-/- mice, including CXCL10, CCL5, CCL3 and CCL4, are also overexpressed in human cases of lethal influenza infections and recognized for recruitment of inflammatory monocytes and neutrophils." (PMID 34691044, 2021). "Interestingly, a recent study provided strong evidence for the protective role of CCR5 antagonism during Chronic Obstructive Pulmonary Disease (COPD) exacerbations caused by influenza in which CCL3 levels but no CCL5, correlated with an exacerbated inflammatory process." (PMID 35126379, 2021). "Neutrophils isolated from influenza-infected mouse lungs were stimulated with CCR1, CCR5, CXCR2, and CXCR3 specific ligands CCL3, CCL4, IL-8, and CXCL11 (100 ng/mL), respectively, and incubated for 4 h." (PMID 31041196, 2019). "Similar targeting approaches have been evaluated for influenza antigens, where the targeted delivery with chemokines such as CCL3 or XCL1, or the TLR ligand flagellin, have resulted in enhanced immunogenicity and protection against influenza." (PMID 26257735, 2015). "CCL25, a chemokine ligand for CCR9, has been shown to play both pro- and anti-inflammatory roles in various diseases, while CCL3 and its receptor CCR5 involvement in leukocyte recruitment into the airway to up-regulate antiviral responses in influenza infection." (PMID 39331702, 2024). "The expression of interferon response genes STAT1, STAT2, Mx1, OASL2, ISG15, chemokines CCL2, CCL3, CXCL9 and CXCL10, and the frequency of neutrophils (CD45+CD11b+Ly6G+) and CD4+ T cells (CD45+CD4+) were all significantly increased in influenza-infected mice when compared to vehicle controls." (PMID 38750107, 2024). "CCL3 and CXCL2 have also been shown to be involved in the recruitment of neutrophils in models of bacterial infection, and are both upregulated in influenza infection." (PMID 35601109, 2022). "By day 7, expression of Ccl3, Cxcl9, Cd86, Il-6, Cd80, and Cxcl11 remained elevated in young adult lung in response to H1N1, while expression of Ccl5, Ccl4, and Cd40 remained elevated in response to either strain of influenza." (PMID 34829979, 2021). "A study of over 15 critically ill patients showed that CCL3 is augmented in lung aspirates of patients, and notably, at the serum level, there was an increment of CCL3 and CCL4 in comparison with mild cases of influenza infection." (PMID 35126379, 2021). "Neutrophils isolated from influenza-infected mouse lungs were stimulated with CCR1, CCR5, CXCR2, and CXCR3 specific ligands including CCL3, CCL4, IL-8, and CXCL11 (100 ng/mL) for 20 min, followed by incubation with a 1:10 ratio of Streptococcus pneumoniae (serotype 3) for 90 min." (PMID 31041196, 2019). "Moreover, targeting by the chemokine CCL3 induced CD8+ T cells that were important for protection against tumor development and influenza-mediated disease in mouse models." (PMID 25122197, 2014).
influenza (continued). "In response to influenza viral entry, epithelial and immune cells induce pro-inflammatory cytokines and chemokines such as interleukin-1β, interleukin-6, tumor necrosis factor α (TNFα), CCL2, CCL3, and CCL5, which recruit macrophages and neutrophils to the site of infection to control the virus." (PMID 39846844, 2025). "Although the chemokine receptor CCR5 does not actively participate in the infection process of influenza, after its activation by the chemokines CCL3/MIP-1α, CCL4/MIP-1β, and CCL5/RANTES, it becomes a key player in the inflammatory milieu that contributes to infection restraint." (PMID 35126379, 2021). "In previous work, we demonstrated that the actions of the chemokine, CCL3, signaling via its receptor CCR1, were crucial for granulocyte recruitment to the lungs in response to PVM infection; CCL3 has also been shown to be a crucial mediator of granulocyte recruitment in mouse models of influenza." (PMID 19298652, 2009).
Obesity (48 papers, 2012 to 2025). Accumulation of substantial excess body fat. "EAT T1 was negatively correlated with adipocyte size and the proinflammatory cytokine MIP-1α (or CCL3), a macrophage-derived mediator of adipose tissue inflammation linked to both obesity and reduced left ventricular function in heart failure patients." (PMID 40850632, 2025). "Increased circulatory and adipose tissue expression of macrophage inflammatory protein (MIP)-1α (CC motif chemokine ligand-3/CCL3) and its association with inflammation in the state of obesity is well documented." (PMID 33050324, 2020). "Taken together, this study provides a novel model for the pathologic role of stearic acid to produce MIP-1α/CCL3 in the presence of TNF-α associated with obesity settings." (PMID 33050324, 2020). "Hyperlipidemia is positively associated with the production of CCL3 in a various mouse models of atherosclerosis and obesity." (PMID 22359597, 2012). "There is an increase in the levels of both pro-inflammatory and anti-inflammatory cytokines in OSA patients with obesity (IF-γ and IL-1RA, respectively) or hypertension (CCL3 and IL-10, respectively)." (PMID 36769452, 2023). "We saw in the immunometabolism component that obesity and known related clinical variables associated with elevated levels of cytokines TRANCE, CCL4, IL18R1, CCL3 and FGF21, for which known links to obesity were discussed." (PMID 33204460, 2020). "We also found increased concentrations of CCL3, IL-1β, and TNFα from among the 38 cytokines, chemokines, and growth factors examined in plasma from ccRCC subjects with obesity versus tumor-free donors with obesity." (PMID 32469992, 2020). "Of 38 plasma proteins analyzed, six (CCL3, IL-1β, IL-1RA, IL-10, IL-17, and TNFα) were upregulated specifically in ccRCC subjects with obesity versus tumor-free controls with obesity." (PMID 32469992, 2020). "Serum levels of numerous obesity-linked chemokines promoting adipocyte proliferation (TIMP-1) and adipose macrophage infiltration (CXCL1, CXCL2, CXCL12, CCL3, and CCL5) were found to be significant predictors of in vivo hippocampal TSPO signals." (PMID 27578213, 2016). "Screening of obesity-associated proinflammatory cytokines and chemokines in subcutaneous white adipocytes demonstrated that BAFF, but not APRIL, upregulated the mRNA expression of multiple proinflammatory mediators, including Tnf, Cxcl1, Ccl2, and Ccl3." (PMID 34006859, 2021). "Thus, results suggest a low-grade inflammatory state in VEGFA, CSF-1 and CCL3 which is related to obesity and BMI." (PMID 33082373, 2020). "Thus, it is likely that stearic acid plays a role in the TNF-α mediated induction of inflammatory marker MIP-1α/CCL3 in the settings of obesity." (PMID 33050324, 2020). "These included changes in 5 immune function-related proteins, among which IL-6 and Ccl3 both decreased by exercise and correlated with obesity and insulin-sensitivity in our mice, likely due to increased and suppressed inflammation by HFD and exercise, respectively." (PMID 31019501, 2019). "Notably, increased adipose tissue levels of multiple β-chemokines (CCL2, CCL3, CCL5, CCL7, CCL8, CCL11) and chemokine receptors (CCR1, CCR2, CCR3, CCR5) have been linked with obesity and associated metabolic inflammation." (PMID 28396851, 2017). "Severity of obesity resulted to be associated with lower plasma levels of oxytocin (p = 0.053), vitamin D deficiency (p = 0.006) and higher plasma levels of IFN-γ (p = 0.004), IL-6 (p = 0.013), IL-7 (p = 0.013), TNF-alpha (p = 0.036) and chemokine ligand 3 (CCL3) (p = 0.013, R2 = 0.03)." (PMID 33809270, 2021). "Other chemokines include but not limited to CCL2 (MCP-1), CCL3 (MIP-1α), CCL4 (MIP-1β), CCL19, CXCL1, CXCL8 or IL-8, CXCL10, and CXCL12 also play an important role in obesity and cancer immunotherapy." (PMID 40863244, 2025). "The increased gene and protein expression of CCL3 (macrophage inflammatory protein 1 alpha) is evident in both the intestine of IBD mice and obesity-inflamed adipose." (PMID 39409054, 2024).
Obesity (continued). "Tumor tissues from HFD-IF mice diminished C5, IL-1β, CCL3, and CXCL2 protein levels compared to those from HFD mice, indicating that IF attenuates obesity-induced inflammatory conditions in the tumor microenvironment." (PMID 38999849, 2024). "This review provides an in-depth analysis of specific chemokines involved in the development of obesity, including C-C motif chemokine ligand 2 (CCL2), CCL3, CCL5, CCL7, C-X-C motif chemokine ligand 8 (CXCL8), CXCL9, CXCL10, CXCL14, and XCL1 (lymphotactin)." (PMID 39334887, 2024). "Our human adipose tissue data show high expression of MIP-1α/CCL3 and TNF-α in obese compared to lean individuals, and these markers are positively correlated in obesity state." (PMID 33050324, 2020). "Thus, we speculate that simultaneously increased plasma levels of free fatty acid, TNF-α and MIP-1α/CCL3 may have the potential to induce significant pathophysiological changes in the adipose tissue compartment in obesity, including changes in insulin sensitivity and lipid metabolism." (PMID 33050324, 2020). "The CC chemokine family members CCL3 and CCL4 have both tens of publications where obesity is mentioned, but with debate on the mechanisms involved and function." (PMID 33204460, 2020). "CCL3 and CCL4 are machophage-derived inflammatory proteins belonging to the CC-motif cytokine family, that show increased expression in diabetic patients and obesity." (PMID 33526854, 2021). "Luminex analysis showed that in the HFD-induced obesity mouse model, there was an obvious increase in serum proinflammation cytokines such as TNF-α, MCP-1, IL-12, IL-1β, IL-6, CCL3, CXCL16, and Resistin, which were further alleviated significantly in the CD226KO group." (PMID 34823548, 2021). "Furthermore, elevated levels of MIP-1α/CCL3 positively correlate with TNF-α and CD163 in fat tissues from individuals with obesity." (PMID 33050324, 2020). "Interestingly, in this current study the mice with obesity and cholangitis were found to have predominately CCL5− neutrophils in the liver as well as higher serum levels of CCL3 and CCL5." (PMID 29449577, 2018). "In summary, our results show that cooperative effect of stearic acid on the TNF-α induced production of MIP-1α/CCL3 depends on TLR4-TRIF-TBK1-IRF3 signaling cascade which suggests an interesting pathophysiological link among stearic acid, TNF-α, and MIP-1α/CCL3 in the state of obesity." (PMID 33050324, 2020).